CD34 (CD34 molecule)
Diseases named in the same sentence as CD34 in open-access papers (continued):
Sharing a sentence is not in itself a finding about the gene and the disease.
latent infection (continued). "Neither UL135 nor miR-US22 is expressed during latent infection of CD34+ HPCs, but each is induced during the reactivation process." (PMID 32759334, 2020). "stopUS28-infected cells failed to maintain a latent infection, as Kasumi-3 or CD34+ cells infected with this mutant produced infectious virus regardless of reactivation stimuli treatment." (PMID 32411622, 2020). "Collectively, these data suggest that a number of HCMV encoded miRNAs are expressed to high levels during experimental latent infection in CD34+ haemopoietic progenitor cells and monocytes; one such miRNA was miR-UL148D, which was routinely observed to be robustly expressed during latent infection." (PMID 27491954, 2016). "However, the current drug compositions are not able to completely eliminate the virus, since HIV-1 is capable of maintaining latent infection in stable reservoirs such as resting CD4+ T cells, naive T cells and CD34+ multipotent hematopoietic stem cells." (PMID 26178009, 2015). "The drastic decrease in UL138 transcript expression in CD14+ cells, which is required for latency establishment in CD34+ HSC, may contribute to the delay in the ability of FIX-ΔLUNA to fully establish a latent infection." (PMID 23300789, 2012). "Since hematopoietic cells, such as Kasumi-3 cells and CD34+ HPCs, infected with viruses, in which US28 expression is abrogated or the US28 signaling domains are mutated, result in lytic rather than latent infection, there is a possibility that the cellular environment is significantly altered." (PMID 35746751, 2022). "We and others have shown deletion of the entire US28 ORF from TB40/E, Titan, and FIX strains of HCMV results in the failure to establish/maintain latent infection of hematopoietic cells, including Kasumi-3 and THP-1 cell lines, as well as primary monocytes and cord blood-derived CD34+ HPCs." (PMID 32411622, 2020). "pp65 localization upon latent infection of CD34+ cells has not been analyzed." (PMID 21429246, 2011). "Notably, CD34+CD38- HSCs demonstrate elevated sensitivity to cell-cycle arrest following HTLV-1 infection in comparison to more mature CD34+CD38+ HPCs, suggesting that HTLV-1 may target stem cells to facilitate a latent infection in vivo by inducing cell cycle arrest to induce cellular quiescence." (PMID 20132553, 2010). "Utilizing an in vitro CD34+ HPC model, we demonstrate that a recombinant virus lacking UL78 protein expression fails to efficiently reactivate from latent infection." (PMID 40501644, 2025). "In Kasumi-3 cells, an undifferentiated leukemia cell line, and in primary CD34+ progenitor cells, a virus lacking US28 was unable to establish latent infection." (PMID 33096622, 2020). "In contrast, using the Merlin clinical isolate, the lack of UL111A did show a decrease in the establishment of latent infection of CD14+ monocytes, as well as in latently infected CD34+ cells." (PMID 25253336, 2014). "Utilizing an in vitro CD34+ hematopoietic progenitor cell (HPC) model, we demonstrate that a recombinant virus lacking UL78 protein expression fails to efficiently reactivate from latent infection." (PMID 41060092, 2025). "Therefore, we also examined levels of viral miRNAs in cells infected with UV-inactivated virus to ensure that viral miRNAs identified in latently infected CD34+ cells and CD14+ monocytes were derived from de novo synthesised RNAs during latent infection and not input virion RNA." (PMID 27491954, 2016).
Stroke (56 papers, 2003 to 2024). Sudden impairment of blood flow to a part of the brain due to occlusion or rupture of an artery to the brain. "Our results showed that the administration of Angpt2 reduced the infarct volume and neuronal loss, the mechanism of which was associated with magnified CD34+ vascular length and area after stroke." (PMID 36358355, 2022). "Outcomes were assessed in a total of 475 patients for SAE (all-cause death) and 393 patients for SAE (recurrent stroke), 137 patients for CD34+ measurements, 389 patients for NIHSS, and 307 patients for Barthel Index." (PMID 34366857, 2021). "Most importantly, given no therapy for ischemic-hemorrhagic stroke risk, the identification of cd45- [cd34+/kdr+]EPCs as juvenile protective factors provides key insight into a translational paradigm to attenuate stroke pathogenesis." (PMID 23383116, 2013). "Pathway-specific array analysis of cd45- [cd34+/kdr+]EPCs: impact of age, stroke susceptibility and sex." (PMID 23383116, 2013). "We observed that DEspR+ and DEspR- cd45- [cd34+/kdr+]EPCs exhibit differential modulation patterns with age, stroke susceptibility and transgenic[hCETP]-induced combined hyperlipidemia." (PMID 23383116, 2013). "In order to explore whether the protective function of Angpt2 in stroke is associated with angiogenesis, which is in reference to CD34 expression level, we first evaluated whether ischemic injury could induce CD34 expression in the injured brain regions." (PMID 36358355, 2022). "In order to assess whether molecular changes occur in parallel to differential changes in subtype-specific numbers, we analyzed pathway-specific changes in freshly isolated DEspR+ and DEspR- cd45- [cd34+/kdr+]EPCs as modulated by age and stroke susceptibility." (PMID 23383116, 2013). "Therefore, the risk of stroke incidence in patients with short stature could be explained by the deficiency of circulating CD34-positive cells, which indicates a deficiency of endothelial repair." (PMID 33549053, 2021). "To determine whether EPCs are juvenile protective factors for microvascular health, we performed a series of quantitative and qualitative analyses of the effects of age, sex and stroke susceptibility on freshly isolated, non-“culture-expanded” cd45- [cd34+/kdr+]EPCs." (PMID 23383116, 2013). "Using a mouse model of stroke following a bone marrow transplant there was a significant increase in BM CD34+ cells found in the ipsilateral hemisphere of the brain 6 weeks and 6 months following stroke injury." (PMID 39075614, 2024). "Immunohistochemical analyses of VEGFr1 and CD34 in the peri-infarct area of ischemic brain showed positive stain in transplantation cell groups of stroke rats." (PMID 38016184, 2024). "Immunohistochemical analyses of DCX and CD34 in the peri-infarct area of ischemic brain revealed larger number (F5,114 = 212.6, ****P < .0001) of CD34 marker in transplantation cell group of stroke animals compared to vehicle-treated groups." (PMID 38016184, 2024). "Immunohistochemical analyses of Iba-1 and CD34 in the peri-infarct area of ischemic brain revealed higher quantities (F5,114 = 274.7, ****P < .0001) of CD34 marker in transplantation cell group of stroke animals." (PMID 38016184, 2024). "Transplanted BM CD34+ cells have also been detected in the vasculature in the acute period following induction of stroke, with these cells displaying endothelial cell markers." (PMID 39075614, 2024). "Previous studies have focused on investigating the efficacy of CD34+ cells as a therapy for adult stroke injury using the middle cerebral artery occlusion (MCAO) model." (PMID 39075614, 2024). "In fact, the number of circulating CD34+ cells present in peripheral blood after a stroke event has been shown to be correlated with the degree of functional and neurological recovery." (PMID 39075614, 2024).
Stroke (continued). "Diminished total antioxidant capacity and CD34 + KDR + and CD133 + KDR + counts in early phases of stroke were associated with disease severity and worse functional outcome at day 90 post-stroke." (PMID 38071215, 2023). "Scrutiny of the correlation between circulating EPC subtypes and the levels of key elements capable of affecting their counts showed that only BL level of angiogenic factor PDGF-BB (r: 0.334; p: 0.043) increased CD34 + KDR + numbers on D90 after stroke." (PMID 38071215, 2023). "In this study, our data provide evidence that EE treatment promoted angiogenesis by increasing the protein expression of VEGF and CD34 in the ischemic penumbra through astrocytic IL-17A during the recovery phase after stroke." (PMID 36873773, 2023). "EE rats treated with anti-IL-17A antibodies exhibited significantly reduced protein expression of CD34 in penumbra at 21 days after stroke compared with those in the EE and EE + isotype groups (P < 0.01)." (PMID 36873773, 2023). "This is the first report to demonstrate a significant therapeutic effect and safety of ia transplantation of CD34+ cells for the chronic phase of stroke." (PMID 35360717, 2022). "To determine neovascularization, we analyzed the expression of CD31+/CD34+ vessels over the course of 28 days in the stroke area using the MELC technology." (PMID 35626695, 2022). "This information was compiled into a flow cytometry standard format (.fcs) file for further analysis, which showed a strong upregulation of CD31+/CD34+ endothelial cells starting at day 14 after stroke induction." (PMID 35626695, 2022). "Quantitative analysis of the MELC data confirmed that the number of CD31+/CD34+ endothelial tip cells was significantly increased in the IC-ANV as compared to neighboring stroke-affected areas, mainly comprising the astroglial scar." (PMID 35626695, 2022). "Secondary outcomes were measured as CD34+ cell counts in periphery blood at day 5, National Institutes of Health Stroke Scale (NIHSS), and Barthel index (BI), Side effects of CSF were taken as the indicator of safety." (PMID 34366857, 2021). "The qualities of CD34+, SAE (all-cause death), and SAE (recurrent stroke) are high while NIHSS and BI are low." (PMID 34366857, 2021). "In clinical investigations, autologous cells isolated from the red bone marrow (mononuclear and MSCs) or peripheral blood (CD34+) are predominantly used in the cell therapy of patients after stroke." (PMID 32962079, 2020). "Nevertheless, the number of clonogeneic CD34 cells released by stroke is much lower than that observed after pharmacological mobilizations by G-CSF of cyclophosphamide." (PMID 33329318, 2020). "As there were no adverse effects, this investigation furthered evidence indicating the safety of using intra‐arterial delivery of BM‐MNC CD34+ cells for stroke therapy." (PMID 32356605, 2020). "Another trial investigated a smaller subpopulation of CD34+ BM‐MNCs in stroke patients for their therapeutic potential." (PMID 32356605, 2020). "The vehicle group induced a significantly higher expression of CD31+/EdU+ and CD34+ endothelial cells than the sham group, suggesting a self-protecting mechanism of spontaneous angiogenesis after stroke insult." (PMID 32698909, 2020). "After ex vivo stimulation of PBMCs by LPS, the CD34 expression per cell (MFI) was significantly upregulated on monocytes on day 1 after stroke compared to healthy controls (p = 0.0172)." (PMID 33329318, 2020). "The cell surface marker CD34 characterizes a population enriched for HSCs, and the proportion of CD34+ cells found in the peripheral blood immediately after stroke has been found to directly correlate with functional recovery." (PMID 33381020, 2020). "Stroke induces a higher number of circulating CD34+ cells during the first 6 days after ischemic insult." (PMID 33329318, 2020).
Stroke (continued). "For example, mononuclear cell (MNC) fractions isolated from HUCB that were depleted of CD34+ stem cells reduced ischemic brain injury in a rat model of stroke." (PMID 29416747, 2018). "Representative images obtained 3 days after stroke showed higher expression of CD34+ and VEGFR-2 in the ischemic cortex and striatum of G-CSF + tPA-treated rats compared with vehicle- and tPA-treated animals." (PMID 29857523, 2018). "Human umbilical cord blood derived CD34+ stem cells are reported to mediate therapeutic effects in stroke animal models." (PMID 26760774, 2016). "Accumulating evidence has demonstrated that CD34+ cells transplantation is a promising therapeutic method against cerebral ischemic diseases, such as stroke, traumatic brain injury, and spinal cord injury." (PMID 24804231, 2014). "The detection of donor Y-chromosome DNA in recipient spTg25+ female rat brain microvessels demonstrates that cd45- [cd34+/kdr+]EPCs integrate into brain microvessels sufficient to delay stroke onset in this ischemic-hemorrhagic stroke-prone rat model." (PMID 23383116, 2013). "Number of juvenile donor non-spTg25- male cd34+/kdr+/cd45- EPCs infused into recipient spTg25+ female rats and corresponding lifespan prior to the onset of stroke." (PMID 23383116, 2013). "In this study, intrathecal injection of the CD34 positive cells into subarachnoid space was performed, thereby migrating more efficiently into the injured area related to stroke through cerebrospinal fluid compared to the intravenous route." (PMID 24187628, 2013). "Real-time RT-PCR pathway-specific array-analysis revealed age-associated gene expression changes in cd45-[cd34+/kdr]EPC subtypes, which were accelerated in stroke-prone rats." (PMID 23383116, 2013). "In our ongoing clinical study, we designed a protocol to determine the safety and potential efficacy of G-CSF mobilization of bone marrow-derived CD34 positive cells in the treatment of patients with a history of stroke." (PMID 24187628, 2013). "In a recent trial we were able to show that stroke leads to spontaneous increases in serum G-CSF and CD34+ cells." (PMID 21887230, 2011). "Co-stainings with Occludin, Von-Willebrand Factor and CD34 demonstrated localization of SVCT2 in brain capillary endothelial cells in the ischemic area after stroke." (PMID 21347255, 2011). "The most important finding in the study is the link between high ICAM-1 and low levels of circulating CD133+CD34+ EPC in early stroke." (PMID 21871109, 2011). "In their randomized, controlled trial they assessed the safety of G-CSF administered for 5 days between Days 7 and 30 after stroke and the effect on circulating CD34+ stem cells." (PMID 21887230, 2011). "However this mobilisation of CD34+ cells has been shown to be muted when patients have been treated with tissue-type plasminogen activator (tPA), the standard treatment option for stroke." (PMID 39075614, 2024). "Preclinical evidence demonstrates that unexpanded CD34+ cells are a promising therapy for neurological conditions where they have been shown to improve multiple indices of injury in rodent models of stroke, Parkinson’s disease and neonatal hypoxic ischemic brain injury." (PMID 39075614, 2024). "Moreover, previous clinical studies have shown that CD34+ BMPCs, including EPCs, are related to a good functional recovery and outcome following a stroke, being consistent with the results of our study." (PMID 38397735, 2024). "When mice with weakened immune systems were given human cord blood-derived CD34(+) cells through their entire bodies, two days after experiencing a stroke, it led to the creation of new blood vessels in the area that lacked oxygen and nutrients due to the stroke." (PMID 37763198, 2023). "Taken together, the data show an accumulation of immune cells in the IC-ANV including dendritic cells and CD4 T-cells, which neighbor the CD31+/CD34+ endothelial tip cells and therefore might support post-stroke angiogenesis." (PMID 35626695, 2022).
Stroke (continued). "Thus, so far, the data show that angiogenesis, as defined by the occurrence of CD31+/CD34+ endothelial tip cells, starts in the areas affected by the stroke 14 days after induction." (PMID 35626695, 2022). "CD34-positive endothelial progenitor cells are important in the formation of new blood vessels in the ischemic brain area, contributing to angiogenesis in the acute stage of stroke and neuroregeneration." (PMID 36035227, 2022). "It has been demonstrated that CD34+, CD56+/Annexin V+ EV, labeled neural progenitor cell-derived vesicles, are also increased over a prolonged period post-stroke compared to patients matched for cardiovascular risk, which the authors interpreted as an indicator for breakdown of blood–brain barrier." (PMID 34819906, 2021). "It has proven to be effective in elevating CD34+ cell counts in periphery blood at day 5, indicating CSF may participate in stroke recovery, but its efficacy in stroke recovery remains detected." (PMID 34366857, 2021). "Using intra‐arterial administration of 100 million autologous, immunoselected CD34+ stem/progenitor cells in five stroke patients within 7 days after severe anterior ischemic stroke (NIHSS score ≥ 8) manifested improvements in NIHSS score and in the modified Rankin scale." (PMID 32356605, 2020). "Furthermore, it is reported that the administration of CD34+ cells after stroke improves neurogenesis through angiogenesis in a mouse model." (PMID 31584974, 2019). "For example, intravenous administration of either HUBC-derived MNCs, MNC fractions enriched for CD34+ stem/progenitor cells, or MNC fractions depleted of CD34+ stem/progenitor cells reduced neurological injury and lesion volume in ischemic rats following stroke." (PMID 29416747, 2018). "However, XSECC treatment up-regulated NeuN protein expression and generated CD34-positive capillaries in the peri-infarct region on the 14th day after stroke, indicating that XSECC not only ameliorated the neuron injury, but also reduced endothelial damage." (PMID 27391841, 2016). "Human umbilical cord blood (HUCB) derived CD34+ stem cells can exhibit neuronal or glial cell properties under defined culture conditions and have been reported to mediate therapeutic effects in animal model of stroke." (PMID 26760774, 2016). "In peripheral blood samples from control and stroke groups, CD34+/Flk1+ cells in stroke animals showed a tendency to increase but were not statistically different from that in sham control animals (n = 5 animals in sham and stroke group, respectively)." (PMID 24503654, 2014). "Interestingly, among cd45- [cd34+/kdr+]EPCs, DEspR+ EPCs are increased in spTg25+ female rats at 2-months of age and decreased by 4-months of age when stroke is imminent at 4.5 months of age." (PMID 23383116, 2013). "FACS analysis revealed that cd45- [cd34+/kdr+] EPCs decrease with progression to stroke in spTg25 rats, exhibit differential expression of the dual endodthelin-1/VEGFsp receptor (DEspR) and undergo differential DEspR-subtype specific changes in number and in vitro angiogenic tube-incorporation." (PMID 23383116, 2013). "Thus, we used antibodies against Von-Willebrand Factor (VWF) and CD34 to confirm endothelial localization of SVCT2 after stroke." (PMID 21347255, 2011). "Granulocyte colony stimulating factor (G-CSF) mobilized human CD34+ cells [1 × 104 cells in 50 μl phosphate-buffered saline (PBS)] were intravenously (iv) or intra-carotid arterially (ia) transplanted 4 weeks after the induction of stroke (chronic stage), and neurological function was evaluated." (PMID 35360717, 2022). "However, distinguishing the cd45- EPC-subset as the per cent fraction of cd45- [cd34+/kdr+]EPCs in total [cd34+/kdr+]EPCs revealed significant decrease in 17 wk-old males and females, ANOVA P<0.0001, thus indicating informativeness of the cd45- [cd34+/kdr+]EPC subset in this rat stroke model." (PMID 23383116, 2013).